NLRP3 (NLR family pyrin domain containing 3)
Description:
Sensor component of the NLRP3 inflammasome, which mediates inflammasome activation in response to defects in membrane integrity, leading to secretion of inflammatory cytokines IL1B and IL18 and pyroptosis. In response to pathogens and other damage-associated signals that affect the integrity of membranes, initiates the formation of the inflammasome polymeric complex composed of NLRP3, CASP1 and PYCARD/ASC. Recruitment of pro-caspase-1 (proCASP1) to the NLRP3 inflammasome promotes caspase-1 (CASP1) activation, which subsequently cleaves and activates inflammatory cytokines IL1B and IL18 and gasdermin-D (GSDMD), promoting cytokine secretion and pyroptosis. Activation of NLRP3 inflammasome is also required for HMGB1 secretion; stimulating inflammatory responses. Involved in the homeostatic wound healing response to tissue injury, a multistep cascade that guides neutrophil migration to necrotic sites while avoiding collateral damage of healthy tissues. ATP released from necrotic cells triggers activation of NLRP3 inflammasome through P2RX7 signaling leading to neutrophil adhesion to the vascular endothelium close to the injury site (By similarity). Under resting conditions, ADP-bound NLRP3 is autoinhibited. NLRP3 activation stimuli include extracellular ATP, nigericin, reactive oxygen species, crystals of monosodium urate or cholesterol, amyloid-beta fibers, environmental or industrial particles and nanoparticles, such as asbestos, silica, aluminum salts, cytosolic dsRNA, etc. Almost all stimuli trigger intracellular K(+) efflux (By similarity). These stimuli lead to membrane perturbation and activation of NLRP3 (By similarity). Upon activation, NLRP3 is transported to microtubule organizing center (MTOC), where it is unlocked by NEK7, leading to its relocalization to dispersed trans-Golgi network (dTGN) vesicle membranes and formation of an active inflammasome complex. Associates with dTGN vesicle membranes by binding to phosphatidylinositol 4-phosphate (PtdIns4P). Shows ATPase activity. Independently of inflammasome activation, regulates the differentiation of T helper 2 (Th2) cells and has a role in Th2 cell-dependent asthma and tumor growth (By similarity). During Th2 differentiation, required for optimal IRF4 binding to IL4 promoter and for IRF4-dependent IL4 transcription (By similarity). Binds to the consensus DNA sequence 5'-GRRGGNRGAG-3' (By similarity). May also participate in the transcription of IL5, IL13, GATA3, CCR3, CCR4 and MAF (By similarity).
Synonyms: CLR1.1; C1orf7; CIAS1; NALP3; PYPAF1; AGTAVPRL; AII; AVP; FCAS; FCU; MWS; DFNA34; FCAS1; KEFH
Chemical probes: MCC950 (high quality)
Gene: Protein-coding gene on chromosome 1 (247,332,331 to 247,449,668, forward strand). Ensembl gene ENSG00000162711.
Subcellular location: Cytoplasm, cytosol; Inflammasome; Cytoplasm, cytoskeleton, microtubule organizing center; Golgi apparatus membrane; Endoplasmic reticulum; Mitochondrion; Secreted; Nucleus
Pathways (Reactome):
Disease: Purinergic signaling in leishmaniasis infection; SARS-CoV-1 activates/modulates innate immune responses; SARS-CoV-2 activates/modulates innate and adaptive immune responses
Cellular responses to stimuli: Cytoprotection by HMOX1; Turbulent (oscillatory, disturbed) flow shear stress activates signaling by PIEZO1 and integrins in endothelial cells
Immune System: The NLRP3 inflammasome
Metabolism of proteins: Metalloprotease DUBs
Genetic constraint (gnomAD): Loss-of-function variants: 47 observed, 93.82 expected, observed/expected ratio (o/e) 0.5, 90% interval 0.4 to 0.64. The upper end of that interval is the gene's LOEUF score, 0.64, which puts it in group 2 of 6, group 1 being the genes least tolerant of losing a copy. Missense variants: 975 observed, 1,325.5 expected, observed/expected ratio (o/e) 0.74, 90% interval 0.7 to 0.78. Synonymous variants: 558 observed, 532.09 expected, observed/expected ratio (o/e) 1.05, 90% interval 0.98 to 1.12.
Homologues: Orthologues: macaque NLRP3 (98% identical), chimpanzee NLRP3 (96% identical), pig NLRP3 (85% identical), mouse Nlrp3 (83% identical), rat Nlrp3 (82% identical), rabbit NLRP3 (80% identical), guinea pig NLRP3 (75% identical). Paralogues in human: NLRP12 (48% identical), NLRP4 (32% identical), NLRP9 (31% identical), NLRP14 (27% identical), NLRP2 (26% identical), NLRP7 (25% identical), NLRP1 (25% identical), NLRP13 (24% identical), NLRP6 (23% identical), NLRC5 (22% identical), NLRP5 (22% identical), NLRP8 (22% identical), and 8 more.
Diseases named in the same sentence as NLRP3 in open-access papers:
NLRP3 is named in the same sentence as 1,111 diseases in open-access papers, as found by Europe PMC text mining. Sharing a sentence is not in itself a finding about the gene and the disease. The quoted sentences say what the papers report.
atherosclerosis (823 papers, 2011 to 2026). A disease characterized by the build-up of fatty material and calcium deposition in the arterial wall resulting in partial or complete occlusion of the arterial lumen. "Particularly, IL-1β is tightly linked to NLRP3 inflammasome activation in adipose tissue, endothelium, and vascular macrophages, and sustained IL-1β production has been implicated in atherosclerosis, type 2 diabetes, and functional decline in older adults." (PMID 41602164, 2026). "Elevated succinate has been associated with mitochondrial dysfunction, apoptosis, and NLRP3 inflammasome activation, as well as chronic inflammatory disorders, such as inflammatory bowel disease, atherosclerosis, and rheumatoid arthritis." (PMID 41550731, 2026). "Existing studies have demonstrated that dysregulated NLRP3 inflammasome activation is closely associated with the pathogenesis of various major human diseases, including atherosclerosis, hypertension, type 2 diabetes, Alzheimer’s disease, and gout." (PMID 41226607, 2025). "The NLRP3 inflammasome and the emerging role of colchicine to inhibit atherosclerosis-associated inflammation." (PMID 39912853, 2025). "In several disease models, Nrf2 has been associated with NLRP3 inflammasome activation, promoting IL-1-mediated vascular inflammation and potentially aggravating conditions such as atherosclerosis." (PMID 40083546, 2025). "Persistent and excessive activation of NLRP3 inflammasome can cause various inflammatory diseases such as Alzheimer’s disease and atherosclerosis." (PMID 40635741, 2025). "In an earlier study, scientists found that mice with atherosclerosis induced by low-density lipoprotein receptor deficiency exhibited reduced atherosclerosis when there was a deficiency of NLRP3 inflammasome elements in their bone marrow cells." (PMID 40830103, 2025). "In has been proved that Col can target NLRP3 for amelioration abdominal aortic aneurysms, atherosclerosis-associated inflammation, and viral myocarditis in mice." (PMID 40523615, 2025). "NOD-like receptor thermal protein domain-associated protein 3 (NLRP3) is a critical inflammatory vesicle involved in the pathogenesis of various diseases, including atherosclerosis, heart failure, and metabolic syndrome." (PMID 40791947, 2025). "Studies show that the NLRP3 inflammasome and inflammation-based diseases, such as Alzheimer disease, atherosclerosis, type 2 diabetes, and liver diseases, are closely linked." (PMID 39982672, 2025). "Beyond its role in atherosclerosis, macrophage-mediated NLRP3 activation has been implicated in the worsening of HF, promoting myocardial fibrosis and impairing cardiac function, even in the absence of overt CAD." (PMID 41516113, 2025). "first demonstrated the role of the NLRP3 inflammasome in promoting atherosclerosis in western diet-fed LDL receptor-deficient mice." (PMID 40040697, 2025). "The NLRP3 inflammasome has been implicated in various conditions, including atherosclerosis, neurodegenerative diseases, and autoimmune disorders." (PMID 39456190, 2024). "For instance, baicalin can reduce ROS production, inhibit p38 MAPK/NF-κB signaling and the NLRP3 inflammasome, and decrease pro-inflammatory cytokines in apolipoprotein E-deficient mice, therefore improving atherosclerosis." (PMID 38339130, 2024). "Studies over the years have suggested that NLRP3 inflammasome is a key predisposing factor for atherosclerosis onset, mediated via cholesterol crystals." (PMID 39337693, 2024). "Citespace analysis revealed that four out of the top 10 most cited references focused on the association between NLRP3 inflammasome and atherosclerosis." (PMID 39022620, 2024).
atherosclerosis (continued). "In contrast, the lack of caspase-1 exhibits a protective effect against the evolution of atherosclerotic lesions, further resonating with the causative association of NLRP3 inflammasome with atherosclerosis." (PMID 38203796, 2024). "CD36 has been observed to be associated with the activation of the NLRP3 and induce atherosclerosis formation." (PMID 39039680, 2024). "Previous studies found that abnormal activation of NLRP3 inflammasome in diabetes patients was associated with atherosclerosis." (PMID 38439031, 2024). "Recently, we showed that HL and Abro1 deficiency decreased atherosclerosis in mice with TET2 CH in which the NLRP3 inflammasome is an important driver of disease." (PMID 38522750, 2024). "Activation of NOD-like receptor protein 3 (NLRP3) is strongly associated with metabolic inflammatory diseases such as diabetes, atherosclerosis, and obesity." (PMID 38439031, 2024). "Epidemiological studies reveal the presence of pyroptotic markers in human carotid atherosclerotic plaques with NLRP3 emerging as a pivotal component implicated in atherosclerosis progression." (PMID 38576612, 2024). "NLRP3 inflammasome has been reported to be associated with a variety of diseases, such as sepsis, gout, Alzheimer’s disease, atherosclerosis, diabetes and the new COVID-19." (PMID 38789414, 2024). "Several signaling pathways implicated in the inflammatory response are associated with atherosclerosis, including the NLRP3 inflammasome, TLRs, proprotein convertase subtilisin/kexin type 9, Notch, and Wnt signaling pathways." (PMID 38803504, 2024). "Abnormal activation of NLRP3 inflammasome is associated with a variety of diseases, such as non-alcoholic fatty liver disease, breast cancer, and atherosclerosis." (PMID 38698431, 2024). "According to a foundational study related to the inflammasome and coronary artery disease development, NLRP3 inflammasomes have been shown to be activated by the cholesterol crystals and are associated with atherosclerosis emergence." (PMID 39039680, 2024). "The NLRP3 inflammasome has been implicated in the heightened sterile inflammatory responses of several metabolic diseases including obesity and atherosclerosis." (PMID 38522750, 2024). "NLRP3 inflammasome plays a key role in inflammatory responses, which is closely associated with lipid formation in vascular, a characterized event for atherosclerosis." (PMID 36627567, 2023). "Of note, loss of OGG1 induces oxidative mtDNA damage and subsequent NLRP3 inflammasome activation, exacerbating atherosclerosis in mice." (PMID 38020895, 2023). "Chronic low-grade inflammation, mainly through the IL-6 and the NLRP3 inflammasome signaling pathways, increases the risk of developing anemia, accelerated atherosclerosis, insulin resistance, diabetes mellitus and osteoporosis in CKD." (PMID 37447158, 2023). "As explained afterward, chronic inflammation is considered an essential part of the underlying multifactorial pathways of atherosclerosis, along with NLRP3 inflammasome activation." (PMID 37175869, 2023). "It has also been reported that NLRP3 gene deletion in mice can significantly lower the risk of atherosclerosis and alleviate Ang II-induced cardiomyopathy by inhibiting mitochondrial dysfunction." (PMID 36978920, 2023). "The NLRP3 inflammasome also plays a crucial role in mediating ten-eleven translocation 2 (Tet2) mutation, which participate in onset of atherosclerosis, which is further explained in the following section on aging." (PMID 37686238, 2023). "NLRP3 responds to various stimuli, and aberrant NLRP3 activation underlies autoimmune and degenerative diseases such as atherosclerosis, Alzheimer's disease, type 2 diabetes, and lupus." (PMID 37575012, 2023). "As for NLRP3, it has previously been linked to cardiovascular diseases, particularly atherosclerosis, which is a significant causative mechanism behind CAD." (PMID 38054817, 2023).
atherosclerosis (continued). "Anomalous NLRP3 inflammasome responses have been linked to multiple health issues, including but not limited to atherosclerosis, diabetes, metabolic syndrome, cardiovascular disease, and neurodegenerative disease." (PMID 37854633, 2023). "Activation of the NLRP3 inflammasome by extracellular metabolites has also been implicated in several other diseases, such as atherosclerosis." (PMID 37507744, 2023). "TMAO is also associated with disease processes in murine models of atherosclerosis, where it is tied to foam cell formation, NLRP3 inflammasome activation, and generation of the proinflammatory cytokines IL-1β, TNF-α, and IL-6." (PMID 37720032, 2023). "recently found that macrophages express the olfactory receptor Olfr2 and all associated trafficking and signaling molecules, which drive atherosclerosis via NLRP3-dependent IL-1β secretion." (PMID 36911736, 2023). "There is increasing evidence that damage-associated molecular patterns (DAMPs), alongside hyperglycemia and hyperlipidemia, are associated with the accelerated onset of atherosclerosis via NLRP3 inflammasomes." (PMID 37175869, 2023). "In pre-clinical studies, MCC950, a NLRP3 inflammasome inhibitor, reversed the accelerated atherosclerosis phenotype in mice with myeloid Tet2 deficiency." (PMID 37446157, 2023). "An excessive NLRP3 inflammasome activation causes tissue damage increasing the risk of developing atherosclerosis." (PMID 37226245, 2023). "The occurrence of atherosclerosis is thought to be caused by almost all the factors that initiate the NLRP3 inflammatory corpuscle (including ROS, ox-LDL, hypoxia, complement, amyloid, and misfolded proteins)." (PMID 37103050, 2023). "Excessive activation of the NLRP3 inflammasome is implicated in developing several inflammatory disorders, such as T2D, atherosclerosis, and Alzheimer’s disease, underscoring the importance of its tight regulation." (PMID 38062308, 2023). "Mice with experimental CHIP show increased pro-inflammatory drive of the NLRP3/IL-1β/IL-6 axis and atherosclerosis, and humans carrying a genetic deficiency in IL6 appear to have reduced cardiovascular risk related to CHIP." (PMID 37209535, 2023). "In conclusion, APN ameliorated NAFLD and atherosclerosis, and the underlying mechanism involved the inhibition of inflammation and NLRP3 activation." (PMID 37198205, 2023). "A growing body of evidence has indicated that nucleotide-binding oligomerization domain-like receptor protein 3 (NLRP3) inflammasomes are closely associated with the pathogenesis of atherosclerosis." (PMID 37836470, 2023). "As deficiency in components of the Nlrp3 inflammasome in the mouse model protects against atherosclerosis development, inhibition of the NLRP3 inflammasome also in humans appears as a promising treatment option." (PMID 37239938, 2023). "The chronic activation of NLRP3 has been implicated in a variety of disorders including atherosclerosis, auto-immune disorders (e.g., multiple sclerosis), and Alzheimer’s disease (Eren and Özören, 2019)." (PMID 37153791, 2023). "An association between NLRP3 and atherosclerosis pathogenesis has been suggested based on evidence such as a large amount of NLRP3 inflammasome-related components, such as NLRP3, ASC, caspase-1, IL1-β and IL-18 detected in atherosclerotic plaques." (PMID 37336361, 2023). "Several studies have demonstrated that idebenone regulates NLRP3 inflammasome activity in rats with occlusion-induced ischemia and in mice with atherosclerosis mediated by apolipoprotein E deficiency." (PMID 35222363, 2022). "In carotid atherosclerosis plaques, the expression of NLRP3 inflammasome components is elevated, implying the association of NLRP3 with atherosclerosis." (PMID 36741414, 2022). "The fact that the NLRP3 inflammasome plays the causal role in driving atherosclerosis is transforming the field of atherosclerosis." (PMID 35641492, 2022).